OR10G9 (olfactory receptor family 10 subfamily G member 9)
Description:
Odorant receptor.
Synonyms: OR10G10P
Tractability: Antibody: UniProt places it where antibodies can reach, with medium confidence; UniProt predicts a signal peptide or a membrane-spanning region; its Gene Ontology location is reachable by antibodies, with medium confidence.
Gene: Protein-coding gene on chromosome 11 (124,023,013 to 124,023,948, forward strand). Ensembl gene ENSG00000236981.
Subcellular location: Cell membrane
Pathways (Reactome):
Sensory Perception: Expression and translocation of olfactory receptors
Gene Ontology:
Molecular function: olfactory receptor activity; G protein-coupled receptor activity
Biological process: detection of chemical stimulus involved in sensory perception of smell; G protein-coupled receptor signaling pathway
Cellular component: plasma membrane; membrane
Genetic constraint (gnomAD): Loss-of-function variants: 1 observed, 0.64 expected, observed/expected ratio (o/e) 1.56, 90% interval 0.32 to 1.92. That is too few expected variants to judge how well the gene tolerates losing a copy. Missense variants: 347 observed, 360.16 expected, observed/expected ratio (o/e) 0.96, 90% interval 0.88 to 1.05. Synonymous variants: 149 observed, 158.54 expected, observed/expected ratio (o/e) 0.94, 90% interval 0.82 to 1.08.
Homologues: Orthologues: macaque OR10G9 (93% identical), dog OR10G9 (87% identical), dog OR10G9C (86% identical), mouse Or10g9 (86% identical), rat Or10g9 (86% identical), mouse Or10g9b (86% identical), rat Or10g9b (85% identical), mouse Or10g7 (85% identical). Paralogues in human: OR10G4 (94% identical), OR10G7 (90% identical), OR10G8 (88% identical), OR10G2 (57% identical), OR10G6 (53% identical), OR10G3 (53% identical), OR10D3 (51% identical), OR10S1 (50% identical), OR2F1 (45% identical), OR2F2 (45% identical), OR2D3 (45% identical), OR5V1 (45% identical), and 80 more.